CALR (calreticulin)
Diseases named in the same sentence as CALR in open-access papers (continued):
Sharing a sentence is not in itself a finding about the gene and the disease.
heart failure (10 papers, 2013 to 2024). Inability of the heart to pump blood at an adequate rate to meet tissue metabolic requirements. "Our objective was to gain insight into the nature of the cause of heart failure in CardiacCRT+ mice with an increased level of calreticulin in adult cardiomyocytes." (PMID 32790682, 2020). "ER stress and calreticulin have been described as important players in heart failure associated with numerous etiologies." (PMID 32323496, 2020). "Increased abundance of calreticulin, an ER Ca2+-buffering chaperone, is associated with human heart failure and is mechanistically linked to the induction of cardiac hypertrophy." (PMID 27441395, 2016). "In a model of canine microembolism of the left anterior descending coronary artery, the resultant heart failure was associated with increased calreticulin and other markers of injurious ER stress including eIF2a phosphorylation (George, Sabbah, Xu, Wang, & Wang, 2011)." (PMID 32323496, 2020). "At these ratios, they regulated the protein levels of the downstream players of the Ca2+ signaling pathway via MDH2 and CALR, thereby balancing Ca2+ homeostasis in the myocardial tissue and mitigating the effects of heart failure." (PMID 39545061, 2024). "Deletion of the calreticulin gene in adult cardiomyocytes results in left ventricle dilation, an impaired electrocardiogram, and heart failure." (PMID 35681417, 2022). "Overexpression of calreticulin in the heart results in cardiomyopathy, arrhythmia, and heart failure." (PMID 32323496, 2020). "We showed previously that ectopic expression of calreticulin in CardiacCRT+ hearts results in the activation of the IRE1α branch of the UPR, and this is associated with cardiac fibrosis and heart failure." (PMID 32790682, 2020). "We previously showed that increased expression of calreticulin in cardiomyocytes of adult mouse hearts (CardiacCRT+ hearts) consistently induces dilated cardiomyopathy, extensive cardiac fibrosis and heart failure." (PMID 32790682, 2020). "This study demonstrates for the first time that inhibition of the unfolded protein response using the pharmacological agent TUDCA decreased cardiac fibrosis in a mouse model of heart failure induced by calreticulin overexpression." (PMID 27441395, 2016). "In this study we created a mouse model with forced cardiomyocytes overexpression of calreticulin (designated throughout this manuscript as HeartCRT+) that have disrupted ER homeostasis in the heart and develop dilated cardiomyopathy and heart failure." (PMID 27441395, 2016). "In summary, up-regulation of the calreticulin gene in the adult heart resulted in rapid development of dilated cardiomyopathy and heart failure." (PMID 23437120, 2013). "Increased calreticulin protein, and thus increased Ca2+ capacity/buffering in the ER in the adult heart leads to a rapid progression to dilated cardiomyopathy and heart failure." (PMID 23437120, 2013). "Here, using transgenic mice, we show that increased expression of calreticulin in the adult heart induces dilated cardiomyopathy and heart failure." (PMID 23437120, 2013). "We show that in adult heart, up-regulated expression of calreticulin induces cardiomyopathy in vivo leading to heart failure." (PMID 23437120, 2013). "However, in vivo, hearts with calreticulin-overexpressing cardiomyocytes experience progressive deterioration of function culminating in heart failure." (PMID 32790682, 2020). "We previously demonstrated experimentally in mice that overexpression of calreticulin in CardiacCRT+ cardiomyocytes led to development of severe cardiac pathology characterized by cardiac hypertrophy, cardiomyopathy, cardiac fibrosis and heart failure." (PMID 32790682, 2020). "We demonstrate here that mice with calreticulin overexpression, which were used to model heart failure, developed extensive cardiac fibrosis due to transient activation of UPR which in turn underlies the subsequent stimulation of the TGFβ1/Smad2/3 signaling pathway." (PMID 27441395, 2016).
heart failure (continued). "Indeed, overexpression of calreticulin in adult mouse hearts results in dilated cardiomyopathy with compromised systolic and diastolic function and heart failure." (PMID 27441395, 2016). "The increased of the calreticulin Ca2+ pool in the adult heart enhances mechanical work potential of cardiomyocytes and activates the IRE1α branch of the UPR all leading to cardiac fibrosis and heart failure." (PMID 37424156, 2023). "Together, these data decipher the specific pro-inflammatory gene activation in DNMT3A mutant monocytes, demonstrating additional molecules, such as proteoglycan serglycin, phagolysosome genes, MCEMP1 and calreticulin, previously undescribed for CHIP-carrying patients with heart failure." (PMID 39196061, 2023). "While overexpression of calreticulin improved cardiomyocyte function in CardiacCRT+ hearts, these hearts paradoxically feature severe cardiac pathology characterized by fibrosis, irregular ECG and heart failure." (PMID 32790682, 2020).
osteosarcoma (10 papers, 2015 to 2025). A usually aggressive malignant bone-forming mesenchymal neoplasm, predominantly affecting adolescents and young adults. "Actinomycin D (dactinomycin), a natural chromopeptide, promotes the release of HMGB1 and IFNG and the exposure of CALR in osteosarcoma cells." (PMID 39759512, 2024). "Paclitaxel is an ICD inducer whose activity is characterized by the release of HMGB1 in osteosarcoma cells and upregulation of CALR in lung cancer cells." (PMID 39759512, 2024). "combined anti-GD2 therapy with anti-CD47 therapy, which upregulated calreticulin expression on the surface of osteosarcoma cells, respectively, as well as promoting phagocytosis of osteosarcoma cells by macrophages." (PMID 39916962, 2024). "Human U2OS osteosarcoma cells expressing a CALR‐RFP fusion protein were implanted in immunodeficient mice to generate tumors that were then treated with DACT." (PMID 32323922, 2020). "However, the presence of redox stress alone does not suffice to translocate calreticulin, as cisplatin treated osteosarcoma cells were unable to expose calreticulin, although significant levels of apoptosis, mitochondrial damage, and ATP release were induced." (PMID 25688334, 2015). "Digitoxin and digoxin, foxglove (Digitalis purpurea)-derived cardenolides, upregulate ICD-related molecules such as DAMPs (HSP90, CALR, and HMGB1) in osteosarcoma cells." (PMID 39759512, 2024). "Septacidin, an L-heptopyranose isolated from Streptomyces fibriatus, enhances CALR exposure and ATP and HGMB1 secretion from osteosarcoma cells." (PMID 39759512, 2024). "After treated with a chemical library in osteosarcoma U2OS cells, higher levels of p-eIF2a, calreticulin (CALR), and HMGB1 were detected in U2OS cells treated with Paclitaxel/Docetaxel than in U2OS cells treated with Fluorouracil/Capecitabine." (PMID 36605427, 2022). "In osteosarcomas, doxorubicin treatment increased the efficacy of immunotherapy with dendritic cells through similar mechanisms of HSP 70 and calreticulin activation, observed in our study." (PMID 31376208, 2019). "However, OXA induced higher phosphorylation of eIF2α and thus higher CALR levels compared to CDDP using U2OS cells, an osteosarcoma cell line." (PMID 32560232, 2020).
lymph node metastasis (9 papers, 2015 to 2024). "Other genes alternating in both primary tumors and lymph node metastasis tumors within individuals include CALR (Calreticulin), FRG1(FSHD Region Gene 1), and ACTG1 (Actin Gamma 1)." (PMID 36653483, 2023). "In GC, previous studies have reported that positive immunohistochemical staining for CALR was significantly correlated with clinical stages and lymph node metastasis." (PMID 28423550, 2017). "tested samples of MPLC with lymph node metastasis (LNM) and found that the genes with the highest mutation frequencies in this pair were MUC16, FLNA, MUC4, FAT3, SETD2, and CALR, which implied that MPLC with LNM may have a unique mutation spectrum." (PMID 39411141, 2024). "Our clinical findings revealed that CALR expression was correlated with the depth of invasion and lymph node metastasis in GC specimens, implying that CALR might involve in the invasion and metastasis of GC." (PMID 35641480, 2022). "In the current study, we discovered that calreticulin (CALR) was highly expressed in GC tissues and related to lymph node metastasis and patient’s terrible prognosis." (PMID 35641480, 2022). "For example, calreticulin (CRT), as an oncogenic protein, was interrelated with TNM staging and lymph node metastasis of nasopharyngeal carcinoma." (PMID 32456355, 2020).
rheumatoid arthritis (9 papers, 2010 to 2025). A chronic, systemic autoimmune disorder characterized by inflammation in the synovial membranes and articular surfaces. "Another isoform of calreticulin exists in the form of citrullinated calreticulin, which was found to modulate immune function in rheumatoid arthritis patients." (PMID 25688334, 2015). "For instance, in rheumatoid arthritis, citrullinated calreticulin is highly prevalent in the synovial tissue." (PMID 25688334, 2015). "Calreticulin was recently reported to bind to TNF family member FasL in the synovial fluid of rheumatoid arthritis (RA) patients." (PMID 25750898, 2015). "In line with this, extracellular calreticulin is present in the synovial fluid surrounding the joints of patients with rheumatoid arthritis." (PMID 25688334, 2015). "Upregulation of CALR, PRDM1, STAT1, TAGAP and TNRC6B has been associated elsewhere with adult rheumatoid arthritis or juvenile polyarticular arthritis." (PMID 24000795, 2013). "Rheumatoid arthritis (RA) is a complex disease triggered by the interaction between genetics and the environment, especially through the shared epitope (SE) and cell surface calreticulin (CSC) theory." (PMID 32849810, 2020). "In addition to their physiological roles, vimentin and calreticulin are targets in autoimmune conditions, like rheumatoid arthritis." (PMID 21209908, 2010). "Previous studies showed that serum CALR was increased in the patients with rheumatoid arthritis (RA) and systemic lupus erythematosus (SLE)." (PMID 32082309, 2020).
chronic myeloid leukemia (8 papers, 2015 to 2023). "Concurrent calreticulin (CALR) mutation and BCR-ABL1 fusion are extremely rare in chronic myelogenous leukemia; to date, only 12 cases have been reported." (PMID 32000382, 2020). "It is becoming increasingly apparent that MPNs harboring CALR mutations (along with the mutations of JAK2 V617F and MPL exon 10) may occur in patients with BCR-ABL1-positive chronic myeloid leukemia (CML) as evidenced by a wave of recently reported cases." (PMID 32038118, 2020).
diabetes (8 papers, 2016 to 2024). "Especially in skeletal muscle and mitochondrial samples, CALR was consistently detected as a valuable indicator of mitochondrial function associated with type 2 diabetes mellitus." (PMID 37943808, 2023). "On the other hand, calreticulin is an indicator of stress in the endoplasmic reticulum, which is linked with the pathophysiology of diabetes." (PMID 35454982, 2022). "Amidst the subset of DEGs, the prominent gene signatures include INS, INSR, DNAJC3, OMA1, GOS2, and CALR which have been reported to be differentially expressed in type 2 diabetes mellitus and/ or metabolic disorders." (PMID 37943808, 2023). "The possible effect of diabetes or antidiabetic treatment on the upregulation of calreticulin and downregulation of enolase needs further investigation." (PMID 35454982, 2022). "We found that PAX4 blunts DNA damage in two models of experimental diabetes, pointing to a general protective mechanism, possibly through preserved ER homeostasis, implicating CALR." (PMID 26813254, 2016). "Calreticulin and alpha-enolase, which might have a role in the interplay between diabetes and EC, need further investigation." (PMID 35454982, 2022). "In line with previous reports, the results of our functional enrichment analysis of PTEN, PRKCA, CALR, MAP2K7 argue for their involvement mainly in the regulation of the oxidative stress response in diabetes." (PMID 39080630, 2024). "Next, we examined the cellular expression of ERp29 and calreticulin, two major MAM-located chaperone proteins that are altered in diabetes." (PMID 28522876, 2017).
lymphoma (8 papers, 2015 to 2024). A malignant (clonal) proliferation of B- lymphocytes or T- lymphocytes which involves the lymph nodes, bone marrow and/or extranodal sites. "Recently, Petrazzuolo and colleagues showed that anaplastic lymphoma kinase (ALK) inhibition causes immunogenic cell damage through the upregulation of CALR in a panel of ALK-driven lymphoma cell lines." (PMID 39767726, 2024). "CALR expression over time was analyzed in ALK-positive lymphoma K299 cell line, showing that, even in this case, surface levels of CALR were reduced after long exposure to low-dose crizotinib (i.e., 120 nM), when compared to the untreated condition." (PMID 39767726, 2024).
autoimmune disease (7 papers, 2019 to 2025). A disorder resulting from loss of function or tissue destruction of an organ or multiple organs, arising from humoral or cellular immune responses of the individual to their own tissue constituents. "Iron chelators, chloroquine and its derivatives, antioxidants, chloroquine derivatives, and calreticulin have been demonstrated to be effective in animal studies for certain autoimmune diseases, exerting anti-inflammatory and immunomodulatory effects." (PMID 38965216, 2024). "Second, we excluded patients with autoimmune diseases who have been reported to have high levels of calreticulin." (PMID 31612071, 2019). "In addition to the phagocytotic effects of CALR in anti-tumor responses, CALR has also an important role in the pathogenesis of infectious and autoimmune diseases." (PMID 32082309, 2020).
chronic neutrophilic leukemia (7 papers, 2014 to 2024). A rare chronic myeloproliferative neoplasm characterized by neutrophilic leukocytosis. "Mutations in CSF3R, SETBP1 and CALR are reported in patients with chronic neutrophilic leukemia (CNL)." (PMID 25316523, 2014).
Obesity (7 papers, 2017 to 2024). Accumulation of substantial excess body fat. "Calreticulin is a multifunctional ER chaperone implicated in obesity and related metabolic disorders, and its secreted form acts as a molecular chaperone for App." (PMID 39329749, 2024). "CALR levels, on the other hand, were comparable between normal weight patients (0.230, 0.206–0.273 ng/ml) and those with obesity (0.233, 0.145–0.422 ng/ml)." (PMID 36213269, 2022). "PDIA3 was higher (p < 0.02) and CALR slightly higher in children with obesity than in controls." (PMID 36213269, 2022). "Calreticulin (CALR) and PDIA3 circulating levels were assessed on 52 pediatric subjects—26 patients with obesity and 26 normal weight controls (4–18 years)—enrolled in a pilot study." (PMID 36213269, 2022).
renal fibrosis (7 papers, 2015 to 2024). A final common manifestation of a wide variety of chronic kidney diseases characterized by glomerulosclerosis and tubulointerstitial fibrosis. "In particular, a proteomic screen that we performed more than 15 years ago, for the identification of novel components involved in the mechanisms of renal fibrosis, led to the observation that Calreticulin is associated with the initiation and progression of kidney fibrosis in a rodent model." (PMID 36440574, 2022). "Here we review the recent advances in our understanding of the regulatory roles of Calreticulin in renal fibrosis." (PMID 36440574, 2022). "Collectively, our previous observations suggest that Calreticulin is a central node in a regulatory axis that controls the initiation and progression of renal fibrosis." (PMID 36440574, 2022). "During renal fibrosis, calreticulin, a multifunctional chaperone of the endoplasmic reticulum (ER) is up‐regulated in tubular epithelial cells (TECs) both in vitro and in vivo." (PMID 29956451, 2018). "While not specifically implicated in S-AKI, NR5A2 regulates the calreticulin gene during renal fibrosis and plays a role in multiple immune pathways including inflammation and tumor-necrosis factor- (TNF) induced cell death." (PMID 39636799, 2024). "In addition, TGF‐β upregulated CALR in vitro in human proximal tubule cells and more recently, mechanisms regulating CALR transcription were elucidated in renal fibrosis." (PMID 37985392, 2023). "We also identified an upstream regulatory mechanism that mediates the transcriptional control of Calreticulin expression during the progression of renal fibrosis, by showing that the druggable orphan nuclear receptor NR5A2 and its SUMOylation is involved in this action." (PMID 36440574, 2022). "In a renal fibrosis rat model, calreticulin abundance is also increased in tubular epithelial cells before ECM deposition and it may promote a profibrotic cellular phenotype." (PMID 27441395, 2016). "Interestingly, in a rat renal fibrosis model induced by unilateral ureteric obstruction, CALR was consistently up-regulated from the earliest stages of the process of renal fibrosis, even before the accumulation of extracellular matrix (ECM) in TECs24." (PMID 26655840, 2015).
cardiac hypertrophy (6 papers, 2013 to 2025). "Calreticulin plays multiple and sometimes counteracting roles in the context of cardiac hypertrophy." (PMID 40564271, 2025). "Previous studies indicated increased expression of calreticulin in cardiac hypertrophy and in the human failing heart, but (to our knowledge) a role for the protein in inducing dilated cardiomyopathy has not been reported." (PMID 23437120, 2013). "It was also hypothesised that calreticulin may have a protective effect on the heart in cases of cardiac hypertrophy." (PMID 40564271, 2025). "Ingenuity Pathway Analysis of miRNA that was identified in calreticulin-deficient ES cells indicates that the top canonical pathways affected in the absence of calreticulin are Wnt signaling, TGFβ signaling, and cardiac hypertrophy markers." (PMID 35681417, 2022). "In a study of the effects of DFMO on cardiac hypertrophy in rats, DFMO not only inhibited ODC and decreased polyamine levels, but also decreased the expression of GRP78, protein kinase R (PKR)-like endoplasmic reticulum kinase (PERK), calreticulin, and caspase-12." (PMID 32697811, 2020).